LIX1 (limb and CNS expressed 1)
Synonyms: C5orf11; Lft
Tractability: No criterion of Open Targets' tractability assessment is met for any kind of drug.
Gene: Protein-coding gene on chromosome 5 (97,091,867 to 97,142,846, reverse strand). Ensembl gene ENSG00000145721.
Subcellular location (Human Protein Atlas): Cytosol; Cytokinetic bridge; Vesicles
Gene Ontology:
Molecular function: protein binding
Biological process: autophagosome maturation
Cellular component: cytoplasm
Genetic constraint (gnomAD): Loss-of-function variants: 20 observed, 28.86 expected, observed/expected ratio (o/e) 0.69, 90% interval 0.49 to 1.01. The upper end of that interval is the gene's LOEUF score, 1.01, which puts it in group 4 of 6, group 1 being the genes least tolerant of losing a copy. Missense variants: 304 observed, 346.18 expected, observed/expected ratio (o/e) 0.88, 90% interval 0.8 to 0.97. Synonymous variants: 120 observed, 127.96 expected, observed/expected ratio (o/e) 0.94, 90% interval 0.81 to 1.09.
Homologues: Orthologues: chimpanzee LIX1 (99% identical), macaque LIX1 (99% identical), pig LIX1 (97% identical), dog LIX1 (97% identical), guinea pig LIX1 (96% identical), mouse Lix1 (95% identical), rat Lix1 (94% identical), tropical clawed frog lix1 (77% identical), zebrafish lix1 (59% identical), Drosophila melanogaster lft (49% identical). Paralogues in human: LIX1L (53% identical), EPG5 (30% identical).
Diseases named in the same sentence as LIX1 in open-access papers:
LIX1 is named in the same sentence as 5 diseases in open-access papers, as found by Europe PMC text mining. Sharing a sentence is not in itself a finding about the gene and the disease. The quoted sentences say what the papers report.
Obesity (1 paper, 2025). Accumulation of substantial excess body fat. "Our analysis revealed a significant upregulation of LIX1 mRNA in patients with obesity compared to controls." (PMID 40652248, 2025). "Additionally, we observed elevated expression of LIX1 in the gastric smooth muscle of patients with obesity, a gene typically restricted to mesenchymal progenitors during fetal development." (PMID 40652248, 2025). "Additionally, in patients with obesity, LIX1 mRNA levels demonstrated an inverse correlation with SM22 protein expression." (PMID 40652248, 2025).
sarcoma (1 paper, 2020). A usually aggressive malignant neoplasm of the soft tissue or bone. "We also demonstrated that LIX1 regulates mesenchymal progenitor proliferation and differentiation by controlling the Hippo effector YAP1, which is constitutively activated in many sarcomas." (PMID 32633461, 2020).
spinal muscular atrophy (1 paper, 2015). A motor neuron disease that affect the muscles, and characterized by muscle weakness and atrophy resulting from progressive degeneration and irreversible loss of the anterior horn cells in the spinal cord (i.e., lower motor neurons) and the brain stem nuclei. "It has been suggested that Lix1 plays a role in radial growth of motor axons observed in feline spinal muscular atrophy." (PMID 26447881, 2015).
tumour (3 papers, 2016 to 2023). "These three properties thus point to the interest of further studies to examine the possible function of LIX1 in tumorigenesis and tumour progression." (PMID 27125505, 2016). "Moreover, immunohistochemical analysis of the tumour tissue showed that LIX1 silencing significantly decreased cell proliferation (KI67)." (PMID 32633461, 2020). "LIX1 expression was highest in patients with relapsed tumour (P = .015)." (PMID 32633461, 2020). "Thus, LIX1 silencing potentiates the anti-tumor effect of imatinib." (PMID 37108337, 2023). "Accordingly, LIX1 silencing mimics the effects induced by MAPK inhibitors and enhances the imatinib anti-tumor effect." (PMID 37108337, 2023). "LIX1 silencing in GIST-T1 cells impaired imatinib-induced MAPK signaling reactivation and enhanced imatinib anti-tumor effect." (PMID 37108337, 2023). "Therefore, we assessed the effect of LIX1 silencing in vivo using the CAM assay, an established in vivo tumour model." (PMID 32633461, 2020).
cancer (1 paper, 2016). A tumor composed of atypical neoplastic, often pleomorphic cells that invade other tissues. "Finally, we have highlighted, through a developmental approach, three properties of LIX1 that could make it essential in cancer research." (PMID 27125505, 2016).